LACTB2 (lactamase beta 2)
Description:
Endoribonuclease; cleaves preferentially 3' to purine-pyrimidine dinucleotide motifs in single-stranded RNA. The cleavage product contains a free 3' -OH group. Has no activity with double-stranded RNA or DNA. Required for normal mitochondrial function and cell viability.
Synonyms: CGI-83
Tractability: PROTAC: ubiquitination databases record sites on it; its protein half-life has been measured.
Gene: Protein-coding gene on chromosome 8 (70,631,109 to 70,669,185, reverse strand). Ensembl gene ENSG00000147592.
Subcellular location: Mitochondrion matrix
Subcellular location (Human Protein Atlas): Cytosol; Golgi apparatus; Nucleoplasm
Gene Ontology:
Molecular function: protein binding; RNA endonuclease activity; single-stranded RNA binding; zinc ion binding
Cellular component: cytosol; Golgi apparatus; mitochondrial matrix; mitochondrion; nucleoplasm
Genetic constraint (gnomAD): Loss-of-function variants: 17 observed, 18.4 expected, observed/expected ratio (o/e) 0.92, 90% interval 0.63 to 1.39. The upper end of that interval is the gene's LOEUF score, 1.39, which puts it in group 5 of 6, group 1 being the genes least tolerant of losing a copy. Missense variants: 216 observed, 236.66 expected, observed/expected ratio (o/e) 0.91, 90% interval 0.82 to 1.02. Synonymous variants: 87 observed, 84.9 expected, observed/expected ratio (o/e) 1.02, 90% interval 0.86 to 1.23.
Homologues: Orthologues: chimpanzee LACTB2 (99% identical), macaque LACTB2 (95% identical), rabbit LACTB2 (89% identical), dog LACTB2 (88% identical), pig LACTB2 (88% identical), mouse Lactb2 (84% identical), guinea pig LACTB2 (84% identical), rat Lactb2 (74% identical), tropical clawed frog lactb2 (72% identical), Caenorhabditis elegans Y53F4B.39 (47% identical), Drosophila melanogaster CG12375 (47% identical).
Diseases named in the same sentence as LACTB2 in open-access papers:
LACTB2 is named in the same sentence as 10 diseases in open-access papers, as found by Europe PMC text mining. Sharing a sentence is not in itself a finding about the gene and the disease. The quoted sentences say what the papers report.
Alzheimer disease (2 papers, 2021 to 2024). A progressive, neurodegenerative disease characterized by loss of function and death of nerve cells in several areas of the brain leading to loss of cognitive function such as memory and language. "From TWAS, we detected an association between an increase in LACTB2 expression and Alzheimer’s disease, which is in agreement with the eQTL study." (PMID 33959712, 2021). "We detected a significant association between Alzheimer’s disease risk and an increase in expression of LACTB2 in CD14+ monocytes in both the Fairfax and in the CTS TWAS." (PMID 33959712, 2021). "In the TWAS analyses of LACTB2, the variant most significantly associated with Alzheimer’s disease risk from GWAS, rs7830986, was also the variant most significantly associated with an increase in gene expression in induced monocytes (LPS24 and IFN)." (PMID 33959712, 2021). "Our analysis identified two novel candidate genes for Alzheimer’s disease risk, LACTB2 and PLIN2/ADRP." (PMID 33959712, 2021). "The association between an increase in expression of LACTB2 and Alzheimer’s disease was detected in monocytes at baseline and after induction with IFN or LPS, suggesting that the association between LACTB2 and Alzheimer’s disease is not specific to monocyte induction." (PMID 33959712, 2021). "LACTB2 and PLIN2 had novel significant associations with Alzheimer’s disease and BIN1, PTK2B, SPI1, MS4A4A, MS4A6E, APOE and PVR are in known Alzheimer’s disease risk loci from GWAS." (PMID 33959712, 2021). "Three of these genes: STX3, LACTB2 and PLIN2 had novel significant associations with Alzheimer’s disease." (PMID 33959712, 2021). "As immunity is important in Alzheimer’s disease, this provides a biological interpretation in immune cells, of genome-wide association studies and implicates two novel genes, PLIN2 and LACTB2, in Alzheimer’s disease." (PMID 33959712, 2021). "Recent study reported that LACTB2 participated in inflammatory response in Alzheimer’s disease." (PMID 38475882, 2024). "We also detected TWAS signals in two genes, LACTB2 and PLIN2 that have not been associated with Alzheimer’s disease previously." (PMID 33959712, 2021).
nasopharyngeal carcinoma (2 papers, 2024). A carcinoma arising from the nasopharyngeal epithelium. "Overexpression of LACTB2 is observed in nasopharyngeal carcinoma and is associated with radioresistance which leads to unfavorable prognosis." (PMID 38475882, 2024). "Overexpression of LACTB2 can induce radioresistance in nasopharyngeal cancer patients." (PMID 38475882, 2024). "LACTB2 is demonstrated to be a prognostic indicator in colorectal cancer and nasopharyngeal cancer." (PMID 38475882, 2024).
colorectal cancer (1 paper, 2024). A primary or metastatic malignant neoplasm that affects the colon or rectum. "Genetic alterations of LACTB2 expression were observed in colorectal cancer." (PMID 38475882, 2024). "Another study revealed that genetic variation of LACTB2 contributes to colorectal cancer formation." (PMID 38475882, 2024).
ovarian carcinoma (1 paper, 2024). A malignant neoplasm originating from the surface ovarian epithelium. "Although our study is innovative in investigating the association between LACTB2 expression and ovarian cancer, it has certain drawbacks." (PMID 38475882, 2024).
ovarian tumor (1 paper, 2024). "RNA-seq data of LACTB2 in OC were downloaded from TCGA and GEO datasets to compare the LACTB2 expression level in normal ovarian tissue and ovarian tumor tissue." (PMID 38475882, 2024).
primary immunodeficiency (1 paper, 2024). "Through the previous enrichment analysis, we found that LACTB2 was mainly associated with chemokine signaling pathway, primary immunodeficiency, cytokine–cytokine receptor interaction, and intestinal immune network for IgA production." (PMID 38475882, 2024).
uterine carcinosarcoma (1 paper, 2024). A usually aggressive malignant neoplasm arising from the uterine corpus and less often the cervix. "Gene alteration of LACTB2 was observed in various cancer types and the highest alteration frequency was in uterine carcinosarcoma." (PMID 38475882, 2024).
cancer (1 paper, 2024). A tumor composed of atypical neoplastic, often pleomorphic cells that invade other tissues. "We explore LACTB2 alteration, including gene mutation, copy number alterations, and structural variant, in pan-cancer level using cBioPortal." (PMID 38475882, 2024). "The result showed that LACTB2 was positively associated with Th2 cells, but negatively associated with Th1 cells in most cancer types." (PMID 38475882, 2024). "β-lactamase-like-protein 2 (LACTB2) has been observed to be associated with various cancers, but its function in OC is unknown." (PMID 38475882, 2024). "In pan-cancer analysis, we observed that LACTB2 expression has significantly positive relationship with Th2 cells, while have negative relationship with Th1 cells." (PMID 38475882, 2024). "We obtained data from TCGA and analyzed the mRNA expression of LACTB2 in 33 types of cancer using GEPIA." (PMID 38475882, 2024). "The prognostic value of LACTB2 was additionally verified in various cancers, including BRCA, HNSC, PAAD, ESCA, and UCEC." (PMID 38475882, 2024). "We further analyzed LACTB2 expressions based on cancer stage, tumor grade, and patients age, respectively." (PMID 38475882, 2024). "Finally, we investigated the relationship of LACTB2 expression and various T cells in pan-cancer level." (PMID 38475882, 2024). "We divided all cancer samples into LACTB2 alteration group and LACTB2 unalteration group." (PMID 38475882, 2024). "That might indicate that LACTB2 alteration can lead to worse long-term outcomes of patients with malignant tumor." (PMID 38475882, 2024). "Hence, there is an urgent need to identify the impact of LACTB2 in the survival of cancer in terms of diagnosis, prognosis, progression and treatment." (PMID 38475882, 2024). "We then investigated the prognostic value of LACTB2 alteration in 33 cancers." (PMID 38475882, 2024). "The significantly negative correlation between LACTB2 expression and Th1 cells infiltration can be seen in all three cancers, while that of Th2 cells were positive." (PMID 38475882, 2024).
tumor (1 paper, 2024). "The results suggested that LACTB2 was positively associated with multiple tumor-infiltrating immune cells." (PMID 38475882, 2024). "Our study reported the potential role of LACTB2 in tumor immunology, thereby highlighting the underlying mechanism by which LACTB2 causes poor prognosis in OC." (PMID 38475882, 2024). "CTPAC database confirmed protein levels of LACTB2 were notably high in primary tumor samples than in normal tissues." (PMID 38475882, 2024). "Previous studies clarified that LACTB2 is a mitochondrial endoribonuclease which can regulate mitochondrial function and promote tumor progression." (PMID 38475882, 2024). "Surprisingly, KEGG analysis showed that LACTB2 expression was correlated with many immune-related pathways, which can facilitate tumor progression." (PMID 38475882, 2024). "Consequently, LACTB2 may regulate the mechanism of tumor immunology to promote OC progression and lead to an unfavorable long-term outcome of patients." (PMID 38475882, 2024). "Hence, our study may indicate that LACTB2 can drive pro-tumoral immunosuppressive program in OC by regulating the tumor-infiltration of Th2 cells." (PMID 38475882, 2024). "Additionally, the expression of LACTB2 in OC was assessed in the GEO database, including GSE12470, GSE18250, GSE137238, and GSE51088, and the results showed that the expression level was significantly higher in tumor tissue than in normal tissue." (PMID 38475882, 2024).
LACTB2 also shares sentences with these, for which no sentence is quoted: Diabetes (1 paper).